NANOG (Nanog homeobox)
Diseases named in the same sentence as NANOG in open-access papers (continued):
Sharing a sentence is not in itself a finding about the gene and the disease.
breast carcinoma (continued). "We initially confirmed that breast cancer MCF-7 cells expressed NANOG, and overexpression of NANOG enhanced the tumorigenicity of MCF-7 cells and promoted the self-renewal expansion of CD24−/lowCD44+ CSC subpopulation." (PMID 23662114, 2013). "To further determine if NANOG is the key component modulating self-renewal capability and tumorigenicity of the tumorigenic breast cancer cells, we carried out the mammosphere-forming assay and orthotropic tumor xenografts experiments in female SCID mice." (PMID 23662114, 2013). "KLF4 acts in concert with OCT4, SOX2, and NANOG in hESCs, but is downregulated in some breast cancer cells compared with normal mammary cells." (PMID 23596564, 2013). "Recent studies indicated that pluripotent gene NANOG involves in regulating self-renewal of breast CSCs, and expression of NANOG is correlated with aggressiveness of poorly differentiated breast cancer." (PMID 23662114, 2013). "Knockdown of NANOG significantly reduced the tumorigenic potentials of various cancer cells including breast cancer." (PMID 23662114, 2013). "In addition, HADS scores were negatively correlated with ZFP36 expression and positively related with LRP5, β-catenin and NANOG expression in cohort 1 breast cancer patients." (PMID 40038255, 2025). "In addition, TAMs secrete high levels of IL-6 increasing stemness markers (i.e. SOX2, OCT3/4 and NANOG) and consequently CSCs expansion in breast cancer cells via STAT3 pathway supporting tumor cells migration and angiogenesis." (PMID 39981232, 2025). "In addition, hypoxic conditions in breast cancer induce m6A demethylation and stabilize pluripotency factor NANOG, thereby promoting breast cancer stem cell phenotypes." (PMID 39000359, 2024). "However, ALKBH5 has been demonstrated to be an oncogene in glioblastoma through the modification of FOXM1, in breast cancer through m6A demethylation of NANOG, and in acute myeloid leukemia via AXL m6A modification." (PMID 35395767, 2022). "In response to hypoxia, hypoxia-inducible factor (HIF)-1α and HIF-2α were stimulated to promote ALKBH5 expression in breast cancer cells; subsequently, ALKBH5 inhibited the m6A level in the 3′UTR of Nanog mRNA and increased NANOG expression, resulting in enhanced breast cancer stem cell phenotype." (PMID 35859892, 2022). "Knockdown or overexpression of ETV4 significantly restrains or fosters breast cancer cell stem-like traits, and ETV4 loss suppresses the expression of stemness markers including c-MYC, OCT4, NANOG, LIN28, suggesting that ETV4 acts as a key regulator in BCSC maintenance." (PMID 34052833, 2021). "Mammospheres or breast cancer cells in hypoxia have higher expression of the KLF4, NANOG, OCT4, and SOX2 genes and CD44 and CD24, which encode pluripotency factors that are required for the maintenance of cancer stem cells, embryonic stem cells, and induced pluripotent stem cells." (PMID 34830821, 2021). "Elevated NANOG promotes breast cancer stem cells enrichment." (PMID 34363020, 2021). "Studies have proved that the overexpression of ALKBH5, an m6A eraser, could decrease the methylation of NANOG mRNA and increase the NANOG protein expression level, thus elevating the proportion of breast cancer stem cells." (PMID 33934391, 2021). "NANOG expression is associated with a poor OS and DFS in breast cancer patients." (PMID 34203746, 2021). "Under hypoxic conditions, HIF-1α and HIF-2α induces ALKBH5 expression, which leads to enhanced mRNA stability of pluripotency factor genes such as NANOG and promotes the self-renewal and proliferation of breast cancer stem cells by increasing the stability of NANOG mRNA110." (PMID 33741974, 2021).
breast carcinoma (continued). "Previous studies reported that ALKBH5 could up-regulate NANOG expression via regulating the demethylation of NANOG in different tumors, like breast cancer, oral squamous cell carcinoma and ovarian cancer." (PMID 33975615, 2021). "Furthermore, the high expression level of NANOG leads to the enrichment of breast cancer stem cells (BCSCs)." (PMID 33362863, 2020). "Increased E2F1 upregulates NANOG, contributing to stemness in breast cancer." (PMID 32244924, 2020). "An increased NANOG mRNA and protein expression promote the breast cancer stem cell phenotype." (PMID 30987661, 2019). "Besides, ALKBH5 decreases the levels of m6A in NANOG mRNA and enhances its stability, leading to an increase of NANOG mRNA and protein levels in breast cancer stem cells (BCSCs)." (PMID 31142332, 2019). "Elevated NANOG promotes breast cancer stem cells (BCSCs) enrichment." (PMID 31801551, 2019). "Overexpression of ALKBH5 could increase the frequency of the breast cancer (BC) stem-cell phenotype by m6A-mediated demethylation of NANOG gene." (PMID 30953473, 2019). "Moreover, HIF-1α induces expression of stemness factors, including Oct-4 and NANOG, and cancer cell plasticity observed in breast cancer is also dependent on HIF-1α." (PMID 29996946, 2018). "In breast cancer cells, shRNA against NANOG reduced cell proliferation and migration." (PMID 29971070, 2018). "m6A demethylation on NANOG mRNA was observed in breast cancer stem cells in response to hypoxia." (PMID 29958477, 2018). "In Du145 cells, the overexpression of HAPTOV1 also associated to significantly increased levels of stemness genes LIN28A, ALDH1A1 and MYC, whereas in PC3 cells it associated to a significant expression of LIN28A, MYC, NANOG and POU5F1 genes, in agreement with reports in breast cancer cells." (PMID 28938627, 2017). "We previously reported that exposure of breast cancer cells to hypoxia induces the ALKBH5-mediated demethylation of N6-methyladenosine (m6A) in NANOG mRNA leading to increased expression of NANOG, which is a pluripotency factor that promotes BCSC specification." (PMID 27590511, 2016). "Additionally, NANOG overexpression is correlated with poor prognoses for colorectal and breast cancer patients, as well as for ovarian cancer patients." (PMID 27225481, 2016). "NANOG overexpression, likewise, increases drug resistance in breast cancer cell lines." (PMID 27225481, 2016). "Two embryonic stem cell genes, GDF3 and NANOG, were shown to be expressed in breast cancer." (PMID 25004928, 2014). "Overexpression of NANOG was shown to characterize an embryonic stem cell-like signature in breast cancer, associated with high-grade estrogen receptor negative tumors, often of the basal-like subtype, and with poor clinical outcome." (PMID 25004928, 2014). "Overexpression of NANOG counteracted the suppressive effect of ugonin J. The current findings suggest that the rhizomes of H. zeylanica can possibly be used as complementary medicine for reducing CSC-mediated breast cancer recurrence." (PMID 23662114, 2013). "We initially investigated whether expression of NANOG plays an important role in breast cancer growth." (PMID 23662114, 2013). "As reported by Ezeh and Hart, NANOG expressed in embryonal carcinomas, seminomas and breast cancer, and could be a valuable marker of tumorigeness." (PMID 21982273, 2011). "Under hypoxia, the expression of ALKBH5 in breast cancer cells was up-regulated by hypoxia-inducible factor, which resulted in a decrease in the m6A modification level of NANOG mRNA, which in turn increased the NANOG protein level and promoted the enrichment of breast cancer stem cells." (PMID 40356909, 2025).
breast carcinoma (continued). "We also showed that the stemness-related transcription factors SOX2 and NANOG, in the context of the TGF-β downstream signaling cascade, are linked to NSDHL, which is consistent with TGF-β-mediated signaling to enrich and maintain the stemness of breast cancer cells." (PMID 39516821, 2024). "Of note, NANOG is essential to the establishment of pluripotency, self-renewal, and reprogramming, which regulate the gene expressions involved in the mitochondrial metabolic pathways required to maintain tumor-initiating stem-like cells in PCa and breast cancer." (PMID 36010983, 2022). "Since it has been reported that NANOG expression is controlled by Hif-1α and that they cooperate, promoting self-renewal in breast cancer stem cells, we therefore hypothesize that the GBM subgroup with HIF1A-KDM5C hyperactivity has a distinctive stemness expression signature." (PMID 36142158, 2022). "In addition, there is evidence that m6A demethylation influences stem cell self-renewal; ALKBH5, which like FTO reduces levels of m6A, was found to increase the stability of NANOG mRNA resulting in an increase in NANOG mRNA and protein levels and enrichment in phenotype of breast cancer stem cells." (PMID 33142830, 2020). "HSP90AA1 is a NANOG transcriptional target that contributes to the maintenance of cancer cell stemness, and its overexpression of HSP90AA1 was associated with unfavorable prognosis in breast cancer, while the inhibition of HSP90 reduces tumor stemness and promotes antitumor immunity." (PMID 33204396, 2020). "Interestingly, CXCR2 could be also a potential cancer stem-like cell marker, as a costaining of some breast cancer cells with NANOG and SOX2 has been reported and also that CXCR1/2 inhibition decreases mammosphere formation." (PMID 32727083, 2020). "Moreover, we discovered that KRT19 regulates CSC reprogramming and drug sensitivity in breast cancer and cancer stem cell-like cells, through mediating stemness (NANOG, OCT4, KLF4, and SOX2) and drug-resistant (ALDH1, ABCG2, ABCC1, and ABCB1) marker expression." (PMID 29747452, 2018). "Consistent with the observations in breast cancer tissues, there was an inverse association between expression level of CRB3 protein and expression levels of β‐catenin protein, β‐catenin downstream factors (CD44 and cMyc) and cancer stem cell‐associated transcription factors (OCT4 and NANOG)." (PMID 29602199, 2018). "The concept that NANOG may reprogram somatic cancer cells via converging on lineage master TFs such as AR/FOXA1 is likely applicable to the NANOG functions in other tumor systems such as breast cancer." (PMID 27867534, 2016). "Thus, it has been suggested that OCT4, SOX2 and NANOG may act as prognostic markers for breast cancer patients." (PMID 26580604, 2015). "To determine whether NOTCH1 contributes to the regulation of NANOG in human breast cancer cells, we treated the basal-like human breast cancer cell line MDA-MB-231 with the γ-secretase inhibitor (GSI) Compound E to interfere with NOTCH1 processing and assayed NANOG expression levels." (PMID 22992387, 2012). "Consistently, tumors from breast cancer patients with low butyric acid displayed lower ZFP36 mRNA and higher LRP5/NANOG/SOX2/Ki67 mRNA compared with patients with high butyric acid." (PMID 40038255, 2025). "Having examined 48 human breast cancer samples, the C1orf50 mean fluorescence intensity (MFI) strongly correlates with both YAP/TAZ (r = 0.80, p < 0.001), and NANOG (r = 0.77, p < 0.001) MFI scores." (PMID 39604563, 2025). "Reduced levels of m6 A modification in breast cancer stabilize KLF4 and NANOG mRNA, leading to the enrichment of stem cells and promoting tumorigenesis." (PMID 40382536, 2025). "Gene expression correlation analysis revealed that USP30 negatively correlates with the expression of stem cell markers such as MMP2, MMP9, MYC, OCT4(POU5F1), NANOG, ALDH1A3, CD133 (PROM1), EPCAM, CD24, and ITGA6 in breast cancer cohorts." (PMID 41306556, 2025).
breast carcinoma (continued). "In the TCGA breast cancer dataset, SDC1 expression was notably correlated with the stem cell biomarkers CD133, CD44, CD24, POU5F1, SMAD2, and NANOG at the transcriptional level." (PMID 41364407, 2025). "Transcription factors such as NANOG, OCT4, and SOX2 are overexpressed in several cancers, including liver, squamous, lung, brain, colon, and breast cancers." (PMID 40647402, 2025). "Evidence suggests that breast cancer stem cells develop resistance through upregulation of stemness and chemo-evasion markers like SOX2, OCT4, NANOG, MDR1, and CD44, following chemotherapy." (PMID 39519572, 2024). "Breast cancer MDA-MB 231 cells were treated with conditioned medium from SPP1-overexpressed TAM, and tumor stem cell markers (SOX2, CMYC, NANOG, OCT4 gene) and PDL1 genes were detected by RT-qPCR." (PMID 38648200, 2024). "In our study, OLE-mALG treatment resulted in increased expression of pluripotency and stemness genes CSCs (27-fold OCT3-4, 10-fold NANOG, 4-fold SOX2) in the 3D model of breast cancer." (PMID 38722566, 2024). "These include EMT (TWIST1, SNAIL1, RUNX1, RUNX2, HIF1, and NOTCH1), breast cancer maintenance (OCT4, SP1, GATA1, ATF1, FOXO3a, ELK1, VDR, and NRF1), pro-metastatic responses (SMAD2/3, HNF1a, GLI1, NANOG, YY1, MYB1, and AP1), and immune modulation (STAT1/3)." (PMID 38398186, 2024). "In breast cancer, an increase in IL6 secretion from TAMs promoted expression of SOX2, OCT4, and NANOG." (PMID 39287565, 2024). "TAM-derived IL-6 enhances CSCs phenotype and expression of CSC specific transcription factors including NANOG, SOX2, and OCT3/4, via activating the STAT-3 signaling pathway in breast cancer cells." (PMID 38254782, 2024). "Research shows that TAM derived IL-6 upregulates the expression of SOX2, OCT4 and NANOG through STAT3 pathway, and induces CSC enrichment in breast cancer." (PMID 38561775, 2024). "EpCAM overexpression was shown to promote the expression of stem cell markers (NANOG, SOX2, and OCT4) in breast cancer cell lines." (PMID 39456890, 2024). "LINC00511 serves as the ceRNA of miR-185-3p to target E2F1 protein and bind it to the promoter region of NANOG, thus promoting transcription and enhancing the stemness of CSC in breast cancer." (PMID 38561775, 2024). "Breast malignant tumors exhibit high expression of stemness-related genes, including SOX2, OCT4, and NANOG in CSCs." (PMID 38802335, 2024). "Previous studies also demonstrated that expression levels of OCT4, NANOG, and SOX2 were higher in poorly differentiated tumors than that of well-differentiated breast cancers, glioblastomas, and bladder carcinomas as well as OSCC." (PMID 37109090, 2023). "Our analysis revealed significantly higher CSC-related stemness genes (OCT4, SOX2, NANOG) (p < 0.0001) and ALDH1A1 (p < 0.0001) in TNBC (GSE30682), in contrast to ER+ luminal breast cancer (GSE5460)." (PMID 38038865, 2023). "The regulation of iron depletion by FTH1 can slow down the self-renewal of breast cancer stem cells, while silencing FTH1 in SKOV3 cells can promote the stemness of cervical cancer cells and the up-regulation of NANOG, SOX2, OCT4." (PMID 38025726, 2023). "Hypoxia induces breast cancer stem cell (BCSC) specification by inducing the expression and/or activity of the pluripotency factors KLF4, NANOG, OCT4, and SOX2." (PMID 37768037, 2023). "This work presented the first insights into visfatin’s role in stemness-related markers in a breast cancer animal model with the induction of OCT4, NANOG, and the SIRT1–SOX2 axis." (PMID 36830834, 2023). "When GPNMB-positive cells form spheres in breast cancer, the expression levels of CSC markers such as SOX2, NANOG, OCT4, CD44, CD133, and FOXO3 are elevated." (PMID 36061142, 2022).
breast carcinoma (continued). "We performed qRT-PCR for the major stemness-related transcription factors, such as NANOG, SOX2, OCT4 and BMI1, as well as the marker CD44, a panel that predicts a transcriptional shift to a stem-like state in breast cancer cells." (PMID 35195687, 2022). "Although stemness and EMT markers, such as SOX2, c-MYC, and NANOG, were downregulated in several YTHDC2-knocked-down breast cancer cells, a common target gene of YTHDC2 in breast cancer cells was not identified." (PMID 36245989, 2022). "This is the case for gastric and breast cancer, where the altered expression of this lncRNA results in the regulation of the transcription factors SOX2, OCT4, and NANOG." (PMID 35954194, 2022). "The activation of this signaling pathway promotes the expression of the stem transcription factors SOX2 and NANOG, as well as CD44, which is one of the reported stem markers in breast cancer." (PMID 35954194, 2022). "Our previously published data also show that compared to adherent breast cancer cells, suspension cultures promote stemness, as shown with real-time quantitative PCR (qRT-PCR) for BMI1, NANOG and CD44." (PMID 35195687, 2022). "Compared to single CTCs in the DNA methylation landscape of 43 breast cancer patients and 3 mouse models, CTC clusters resulted in hypomethylation in the binding sites of OCT4, NANOG, SOX2, and SIN3A." (PMID 36010983, 2022). "In order to determine the mechanism governing the regulation of CSC by piR-823 in breast cancer cells, stem cell-regulating factors including OCT4, SOX2, KLF4, NANOG, and h-TERT were examined in MCF-7 cells after knockdown or overexpression of piR-823." (PMID 33791297, 2021). "Positive controls showed expected staining for OCT4 and NANOG in seminoma, SOX2 in skin, KLF4 in breast carcinoma, and c-MYC in normal colon." (PMID 33816543, 2021). "Positive staining was demonstrated on sections of control human tissues: tonsil for CD44, seminoma for OCT4 and NANOG, skin epidermis for SOX2, breast carcinoma for KLF4, and colon mucosa for c-MYC." (PMID 34685477, 2021). "HIF-1α can induce pluripotent stem cell inducers, such as OCT4, NANOG, SOX2, KLF4, c-MYC, and microRNA-302, in 11 cancer cell lines (derived from prostate, brain, kidney, cervix, lung, colon, liver, and breast cancers)." (PMID 34064635, 2021). "In breast cancer, ALKBH5 has been shown to promote tumourigenesis by decreasing adenosine methylation in KLF4 and NANOG mRNAs, enhancing their stability in breast cancer stem cells." (PMID 33461542, 2021). "Elevated levels of ALKBH5 demethylate the transcripts of pluripotency-related gene Nanog homeobox (NANOG) thereby increasing its expression, and inducing breast cancer stem cell phenotype." (PMID 34484567, 2021). "Downregulation of ALG3 reduced, while upregulation of ALG3 increased NANOG, OCT4 and SOX2 expression in breast cancer cells under radiation treatment." (PMID 33931075, 2021). "Genes related to proliferation (MKI67, CCNA2), differentiation (EPCAM, CDH1), epithelial to mesenchymal transition (VIM, SNAI2), pluripotency and breast cancer stem cells (SOX2, NANOG, CD44) were included." (PMID 34090457, 2021). "Taking into account these affirmations, it will be very interesting to assess the role of NANOG and CXCR4 in other cancer cell lines apart from glioblastoma, like breast cancer cells." (PMID 34638956, 2021). "β-catenin binds POU5F1/OCT4 in embryonic stem cells, it stimulates human NANOG promoter activity and it regulates SOX2 activity in breast cancer cells." (PMID 34199594, 2021). "CCAT1 increased expression of the stemness markers NANOG, SOX2, OCT4 and ALDH1A1, and promoted proliferation, invasion, and migration in the breast cancer cells." (PMID 32244924, 2020). "In breast cancer cells, the m6A demethylase, ALKBH5, reduced the level of m6A modification in NANOG mRNA, which subsequently stabilized NANOG mRNA and thus promoted breast cancer stem cell phenotypes." (PMID 32101138, 2020).